CD4 (CD4 molecule)
Diseases named in the same sentence as CD4 in open-access papers (continued):
Sharing a sentence is not in itself a finding about the gene and the disease.
tumor (continued). "This shows how CSCs even present in low numbers during tumor initiating or relapse phase, are able to evade immune destruction by converting CD4+ T cells to immunosuppressive Treg cells." (PMID 38038865, 2023). "Myeloid cells with metabolizing arginase-1 and CD4+T cells related to tumors were found in the parenchymal region of the tumor." (PMID 36459212, 2023). "CD4+ T cell-derived or exogenous IL-18 promotes proliferation and anti-tumor activity of CD8+ T cells and chimeric antigen receptor (CAR)-T cells." (PMID 36932407, 2023). "In aggregate, these results indicated that the ability of adoptively transferred CD4+ T cells to indirectly eradicate IFN-unresponsive, MHC-deficient tumour cells involved the remote action of nitric oxide released by IFN-activated tumouricidal myeloid cells." (PMID 37316667, 2023). "Combining PD-1 blockade with 90Y-NM600 led to an unexpected decrease in anti-tumor efficacy that was found to be due to increased activity of PD-1-expressing CD4+ Treg that persisted in tumors despite TRT treatment." (PMID 36678880, 2023). "The whole cells cancer vaccine contains a broad range of tumor-associated antigens (TAA), and is enriched with antigenic epitopes of CD8+ T cells CD4+ T cells and thus elicits a comprehensive and effective anti-tumor response." (PMID 37435064, 2023). "Following IFN-γ production by NK or T-cells, mregDCs can produce IL-12 and stimulate anti-tumor immunity (CD4 or CD8 T-cells, NK cells)." (PMID 37190135, 2023). "Tumor immunotherapy promotes transmission of signals on dendritic cells from CD4+ T cells to CD8+ T cells, and finally enhances the activity of cytotoxic T lymphocytes." (PMID 37940859, 2023). "In chemically-induced malignant transformed tissues as well as in xenograft tumor tissues, Huaier treatment significantly increased CD4+ T cells, CD3+ T cells and CD8+ T cells that played indispensable roles in mounting anticancer responses." (PMID 37449208, 2023). "Transfer of autologous ex vivo expanded tumor-infiltrating lymphocytes (TIL) comprising tumor-reactive CD4+ or CD8+ T cells has generated durable responses also in late-stage cancer patients." (PMID 37849763, 2023). "RORγ+ cells comprise 15% of the CD4+ T cell fraction in lymphocytes that have infiltrated various human tumor types." (PMID 37892995, 2023). "The results revealed that the ROD group had the highest levels of CD4+, CD8+ T cells and M1 polarized tumor-associated macrophages (M1-TAMs), while the R and NS groups had the lower counts (p < 0.001)." (PMID 37919724, 2023). "Serial sections from the tumor were incubated first with PD-L1 antibodies to confirm the expressions of PD-L1 and then with CD4 and CD8 antibodies." (PMID 36604635, 2023). "Although the percentages of CD4+ cells were similar in oe-FOSL2 and vector tumour samples, the number of CD4+CD25+ Foxp3+ Tregs was increased in oe-FOSL2 tumours." (PMID 37380804, 2023). "The HS of the CD16 + cells, Dendritic cells,pDC cells, B cells, and CD4 + Tconv cells in the tumor tissue were lower than those in normal tissue (P < 0.05), while NK cells, CD8 + cells, and CD14 + cells vice versa (P < 0.05)." (PMID 36627705, 2023). "Immune cell profiling of tumor tissues revealed that combining sICAM‐1 with anti‐PD‐1 led to the expansion and activation of CD4+ T and CD8+ T cells in CT26 tumor models." (PMID 37097643, 2023). "Tumor CD4 cells showed a trend towards reduced expression intensity of PD-L2 (p 0.147) but not PD-L1." (PMID 36251031, 2023). "Postradiation OCSCC exhibited more adverse pathologic features (perineural invasion, worse pattern of invasion, and tumor budding), higher PD-1 expression, and higher gene expression of CD4 and TGF-β compared with sporadic OCSCC." (PMID 37459093, 2023). "The infiltration of CD8 + activated T cell and CD4 + Th1 cell was also reported to exert tumor inhibition functions in tumors." (PMID 37237274, 2023).
tumor (continued). "Additional immune features of note included a striking increase in the CD4/CD8 T cell ratio in the tumor samples compared to STM and marked changes in the relative abundance of effector T cell subsets." (PMID 38074634, 2023). "A distinct difference between the clinical application of personalized vaccines and our model system was our ability to functionally screen neoantigens for CD8+ and CD4+ T cell responses by IFN-γ ELISpot specific to the Panc02 tumor line." (PMID 38063199, 2023). "After coculturing with tumor cells, CD4+ and CD8+ T cells built significantly more VISTA, and VISTA expression with the supernatant was similar." (PMID 37190254, 2023). "Supporting studies have demonstrated the anti-tumor effect of activated CD4+ memory T cells in other cancers." (PMID 37781029, 2023). "Tumor-promoting CD4+CD25+FOXP3+ T-regulatory cells (Tregs) have been described to abolish host defense mechanisms by impeding the activities of other immune cells including effector T cells." (PMID 38038865, 2023). "We observed an increased CD4/CD8 ratio in our research, suggesting that CIRT was likely to improve anti-tumor immunity and be associated with better prognosis for localized prostate cancer patients." (PMID 36138265, 2023). "In contrast to the UM samples with WT BAP1, macrophages, CD4+ T lymphocytes, CD8+ T lymphocytes, tumor-associated fibroblasts, and mast cells had higher infiltration in the UM samples with MUT BAP1." (PMID 37710185, 2023). "Additional investigations revealed that dual therapy induced an overwhelming infiltration of T cells into the tumor as well as changes in CD4+ T cell subsets." (PMID 36881480, 2023). "TCL contains many neoantigens, and immunization of mice with new epitopes restricted by immunodominant MHC-II molecules can trigger strong tumor-specific CD4+ T-cell and CD8+ T-cell responses." (PMID 36776837, 2023). "In ICB-treated mouse models of orthotopic pMMR CRLM, the proportion of activated CD8+ T cells, CD4+ T cells and cDCs is lower in metastatic tumours than in subcutaneous tumours." (PMID 37480104, 2023). "Anlotinib was shown to increase tumor vascular vessel formation, at least partially, by preventing the early exhaustion of CD4+ T cells." (PMID 36250532, 2023). "Tumor-infiltrating lymphocytes (TILs) are lymphocytes specific for autologous tumor cells with multiple phenotypes (CD4+ T, CD8+ T, Treg, and B cells)." (PMID 37529035, 2023). "As expected, tumor-bearing mice showed significant decrease in blood and splenic CD4+ and CD8+ T cells, increased splenic macrophages, as well as increased g-MDSC/neutrophils populations in the blood, independent of treatment with FK506." (PMID 38052214, 2023). "We next determined the T cell subsets involved in the natural NeoAg-specific immune response by assessing the reactivity of CD4+ versus CD8+ T cells isolated from mice immunized with SCC VII tumor cells." (PMID 37655661, 2023). "As predicted from the functional effects of CD4+ T-cell help, the transcriptomic signature of “helped” cDC1 correlates with tumor infiltration by CTLs and Thelper(h)−1 cells, overall survival and response to PD-1-targeting immunotherapy." (PMID 36639382, 2023). "CD8+ T cell effector activity, proliferation, and recruitment to the tumor site are largely augmented by tumor-specific CD4+ T cells via IL-2 signaling." (PMID 38328405, 2023). "Currently, tumor antigen-specific CD4+ T cells are thought to be essential for the clinical benefit of cancer vaccines as the induced CD8+ CTLs alone are not sufficient." (PMID 37727790, 2023). "A direct association of VD t1 with CD4+ and FOXP3+ TILs in the invading tumor front was noted (p = 0.05 and 0.01)." (PMID 36900270, 2023). "Depletion of eosinophils in ΔdblGATA mice increased tumor burden, and the cellular composition of the lungs showed lower CD4 + and CD8 + T cell infiltration." (PMID 37587450, 2023).
tumor (continued). "OX40 was also expressed by conventional CD4 T cells, although positive cells were reduced in the tumor of mice treated with RT+CTLA4i." (PMID 37620372, 2023). "The immune cells that process and present tumor antigens, such as DCs, and the cells killing tumors, such as NK cells, CD4+ T cells, and CD8+ T cells, were all significantly increased in the spleens of ME49Δgra5-vaccinated mice." (PMID 37426671, 2023). "Another line of immune cells, IL-17 producing CD4+ T-cells (Th17), are stimulated and expanded by the expression of TGF-β, IL-6 and IL-23 in the tumor micro-environment, and are believed to be implicated in tumorigenesis." (PMID 37681925, 2023). "Tumor‐infiltrating CD4+ T cells in recurrent tumors express higher levels of inhibitory receptors and have a lower capacity of cytokine production." (PMID 37829505, 2023). "Among the four cell subgroups, we found that CD8+ T cell and CD4+ T cell had a higher percentage both in tumor samples and normal samples than the other two cell subgroups, and CD8+ T cell occupied the highest proportion among the four cell subgroups." (PMID 37534253, 2023). "The emergence of single-cell RNA sequencing technology has advanced our understanding of the functional subgroups of CD4+Treg in tissue microenvironments, particularly in tumor-infiltrating sites." (PMID 38250084, 2023). "Depending on the cytokine milieu to which they are exposed, CD4+ T cells can differentiate into several phenotypically different subsets with very divergent effects on tumor progression." (PMID 36980536, 2023). "Subsequent analyses showed production of IFNγ and GzmB- and Perforin-dependent killing of tumor cells by tgTCR CD4+ T cells in a MHC class II-dependent manner." (PMID 37965314, 2023). "FK228 is a histone deacetylase inhibitor that can upregulate the expression of PD-L1 in tumor cells and enhance the antitumor effect by affecting the activity of CD4+ and CD8+ T cells." (PMID 37875976, 2023). "In breast cancer, miR-141 inhibited tumor cell proliferation by suppressing MAP4K4 expression, which was associated with an increase in tumor infiltration by CD4+ T lymphocytes." (PMID 37223681, 2023). "CXCL-9 is an IFN-γ inducible chemokine that attracts various CXCR-3-expressing effector immune cells including CD8+ and CD4+ T-cells and also NK cells, and thereby changes the tumor microenvironment to an anti-tumor phenotype." (PMID 37958417, 2023). "Stimulation with WGP led to DC maturation and cytokine secretion, promoted CD4+ T cells to differentiate into Th1 cells, and induced tumor-specific CTLs." (PMID 36713833, 2023). "cDC2 are more heterogenous than cDC1 cells in tumors but are believed to play a role in recognizing exogenous tumor antigens and presenting them to CD4+ T cells on MHC-II." (PMID 38263981, 2023). "The potent lymphocyte attractor ligand CCL5 is reported to be prospectively upregulated in tumor-infiltrating CD4 + t cells following an initial immune stimulation to maintain t cell infiltration." (PMID 36906603, 2023). "We observed that CD4+ T cells exhibited less infiltration in tumor tissues with high ADAR1 expression." (PMID 37162299, 2023). "In contrast, regulatory CD4+ T cells (Tregs) can promote cancer development and progression by inhibiting the immune response against tumours." (PMID 37313656, 2023). "This interaction also hampers the function of tumor-infiltrating CD4+/CD8+ T cells (CD4+/CD8+ TILs) and reduces the production of cytokines such as tumor necrosis factors, IFN-γ and Interleukin-2." (PMID 38003938, 2023). "Clonal expansion is another indicator of tumor reactivity and has been observed in CD4 CTLs in cancer patients." (PMID 37185301, 2023). "CD4+ T cells are essential for tumor control to prevent tumor initiation and facilitate clearance of premalignant and malignant cells." (PMID 37608898, 2023).
tumor (continued). "Achieving efficient spatiotemporal coordination of antigen cross-presentation and immune effects, BANSs induced the production of CD4+ T helper (Th1) cells and CTLs, resulting in effective tumor growth inhibition." (PMID 37024939, 2023). "A mouse model of curative viral onco-immunotherapy found that peritoneal tumor challenge following cure identified an oligoclonal anti-tumor memory CD4 and CD8 T-cell response." (PMID 37033929, 2023). "Cellular and molecular profiling demonstrates that tumor control is associated with elevated HLA-II expression on tumor cells and increased CD4 CTLs in the blood and tumor of HIS mice." (PMID 37185301, 2023). "For example, the infiltration degree of CD8+ T lymphocytes in tumor tissues, the expression status of PD-L1 in tumor cells, the number of CD4+ T lymphocytes and the composition ratio of other immune cells in the microenvironment." (PMID 36759842, 2023). "CD4+ helper T lymphocytes support tumor cell death mediated by CD8+ T lymphocytes, thus participating in the development of the antitumor immune response." (PMID 37108109, 2023). "GALNT10 encodes for polypeptide N-acetylgalactosaminyltransferase 10, which is associated with the increased regulatory CD4+ T cell infiltration and decreased granzyme B expression in CD8+ T cells in tumor tissues." (PMID 36609529, 2023). "Mature DCs present tumor-derived peptides on MHC class I and II molecules to CD8 + and CD4 + T cells, with costimulatory "signal 2" interactions enhancing the development of tumor-specific T cell responses." (PMID 37420174, 2023). "We also observed a potent innate immune response and increased tumor infiltration by M1-phenotype macrophages, CD4+ and CD8+ T cells, NK cells, and Tregs." (PMID 37345658, 2023). "Denardo and colleagues demonstrated that IL-4, specifically expressed by CD4+ T lymphocytes, reinforces a pro-tumor behavior in TAMs which activates epidermal growth factor receptor signaling to fuel metastasis to the lungs." (PMID 37440925, 2023). "ACM derived from OGJ patients with late-stage tumours significantly increased the expression of CD62L on the surface of CD4+ T cells compared with untreated cells (untrx: 26.73 ± 11.18 vs. late-stage: 37.97 ± 12.9%, p = 0.01)." (PMID 36790524, 2023). "Among them, CD4+ and CD8+ T cells, together with NK cells, dendritic cells, and M1 tumor-associated macrophages (TAMs), promotes cell killing." (PMID 36980534, 2023). "While CD4+ T cells primarily mediated anti-tumor immunity and Tregs primarily mediated pro-tumour immunity, these were consistent with our previous result that patients with high TSPAN7 expression had better prognosis." (PMID 36845098, 2023). "It is worth mentioning that CD4+FoxP3+ Tregs surrounding S15+ tumor cells had the most significant prognostic values (P = 0.008)." (PMID 37674198, 2023). "Consistent with previous findings, the exhaustion marker CD39 was upregulated in tumor-infiltrating CD4+ and CD8+ T cells and macrophages compared with cells isolated from adjacent liver tissue and blood." (PMID 37388918, 2023). "The results showed that the high expression of gene signature groups exhibits elevated levels of immunosuppressive cells, such as Tregs and macrophages M0, and low infiltration of anti-tumor cells, including CD4+ and dendritic cells." (PMID 38099288, 2023). "Although CD8+ T cells are the most studied effector cells of cancer immunotherapy, CD4+ T cells are also required for mounting an efficient anti-tumor immune response." (PMID 36831636, 2023). "The production of CD4+ T follicular helper cells requires B cells that recognize tumor neoantigens, and their collaboration promotes anti-tumor CD8+ T cells responses." (PMID 37426671, 2023). "We found that at k = 30, the selected cells were predominantly from the CLR group and composed of macrophages (16%), tumor cells (14%), smooth muscle (10%), stroma (7%), and CD4+ T cells CD45RO+ (7%)." (PMID 37720335, 2023).
tumor (continued). "In a B16F10 melanoma model, transfer of TIGIT-deficient Tregs along with wild-type CD4+ and CD8+ T effector cells into tumor-bearing Rag mice has also been shown to markedly curtail tumor growth." (PMID 37291608, 2023). "Administration of L-1 to mice bearing MC38 or CT26 tumors substantially suppresses tumor growth, particularly when combined with anti-PD-L1, and augments the presence of tumor-associated macrophages as well as CD8+ and CD4+ T cells." (PMID 38022587, 2023). "Treg cells are immunosuppressive subsets of CD4+ T cells expressing Foxp3, CD25 and CD4, which can inhibit antitumor immune responses in tumor patients." (PMID 38022658, 2023). "The three ICI immune subtypes and three ICI gene clusters had notable differences in the types of immune infiltrating cells, including CD4 + T cells, CD8 + T cells, DCs, NK cells, memory B cells, and tumor-associated macrophages (TAMs)." (PMID 35780460, 2023). "CD40 activation leads to an increase in CCL5 expression by TAMs allowing the recruitment of CD4+ T cells into the tumor, which are essential for tumor regression." (PMID 37143666, 2023). "We also identified two clusters of tumor-specific CD4+ T cells, including a population of Tregs expressing the Treg-defining transcriptional factor Foxp3." (PMID 37143122, 2023). "Important to note, MHC Class II-dependent CD4+ CTL were subjected to inhibition by tumor-resident Tregs." (PMID 37965314, 2023). "Tumor-specific CD4+ and CD8+ effector T cells effectively kill cancer cells and are critical for an effective antitumor response." (PMID 36892747, 2023). "Together, these data suggest that the addition of CD4+ T cell depletion to PD-L1 blockade therapy promotes the tumor infiltration of CD8+ T cells and the eradication of PD-L1+ immune cells in MCA38 tumors." (PMID 36969495, 2023). "In the tumor microenvironment, Tregs (CD4+ FOXP3+ regulatory T cells), formerly known as suppressor T cells, promote cancer immune evasion through the suppression of antitumor T effector responses." (PMID 37828948, 2023). "These putative positive correlations show that a high CDK1/PBK/CHEK1 expression promotes tumor growth, aggressiveness, and immune evasion through the increased recruitment of T Cells CD4+ Th2, MDSCs, and TAM-M2, all of which have pro-tumor effects." (PMID 38003585, 2023). "We also found that there were high abundance of CD8+ T cells, CD4+ memory resting T cells, and macrophages M0/M1/M2 both in normal and tumor tissues." (PMID 37280525, 2023). "Such low immunogenic sub-clones are often affected by loss of antigen presentation, due to a defective antigen- presenting machinery, hampering the recognition of tumor antigens by conventional (CD4+ and CD8+) and unconventional T cells." (PMID 37654484, 2023). "We have cross-referenced the genomic and RNA-seq data with CD8+ and CD4+ IHC staining on the same tumour specimens to define and validate a novel paediatric-specific gene signature that identifies tumours infiltrated by CD8+ T-cells." (PMID 37013636, 2023). "Consistent with the data from the s.c. models, the number of CD38+CD39+CD4+ TILs in tumor foci in the lungs of mice injected with B7-H3 knockdown was increased compared to mice injected with control cells." (PMID 36869048, 2023). "Conversely, regulatory T cells (Tregs), a subtype of CD4+ T cells characterized by the expression of CD25 and forkhead box P3 (FoxP3), are capable of suppressing the tumor immune response and are associated with the metastasis and recurrence of HCC." (PMID 37275909, 2023). "CD4+ memory T cells are a subset of tumor-infiltrating T cells capable of continuous immune surveillance to provide long-term immunity." (PMID 36776859, 2023). "From the histopathological analysis of HCC tissue, TIM-3 was observed with strong expression on CD4 and CD8 T-cells, as well as on tumor-associated macrophages (TAMs) on tumor tissue when compared to normal hepatic parenchyma." (PMID 37174089, 2023).